PRKAG2 (protein kinase AMP-activated non-catalytic subunit gamma 2)
Diseases named in the same sentence as PRKAG2 in open-access papers (continued):
Sharing a sentence is not in itself a finding about the gene and the disease.
Hypertension (5 papers, 2012 to 2024). The presence of chronic increased pressure in the systemic arterial system. "We know that up to 50% of PRKAG2 pathogenic mutation carriers were also reported to have hypertension." (PMID 36556501, 2022). "The association of genetic variants at PRKAG2 with higher risk for CKD and hypertension as well as lower risk for kidney stone disease suggests a biological link between PRKAG2 and UMOD and suggest that PRKAG2 represents another target to modulate uromodulin-mediated risk of CKD." (PMID 35446786, 2022). "Our results imply that genetic variants at PRKAG2 are associated with higher risk for CKD and hypertension, as well as lower risk for kidney stone disease, through the same biological context as UMOD." (PMID 35446786, 2022). "Second, shared association patterns of uromodulin-associated genes with complex traits and diseases are plentiful and place the PRKAG2 and UMOD loci into the same context with respect to their associations with CKD, hypertension, and kidney stone disease." (PMID 35446786, 2022). "Interestingly, genetic associations with antibody-based circulating uromodulin at the PRKAG2 and UMOD/PDILT loci shared a very similar pattern of colocalization with numerous kidney-related traits (creatinine, cystatin C, urea, eGFR, CKD, urinary calculus, DBP, SBP, hypertension)." (PMID 35446786, 2022).
chronic kidney disease (4 papers, 2018 to 2025). Impairment of the renal function secondary to chronic kidney damage persisting for three or more months. "Shared association patterns with complex traits, including chronic kidney disease and blood pressure, placed the PRKAG2 locus in the same pathway as UMOD." (PMID 35446786, 2022). "Of interest, coexistent chronic renal disease, present in two female carriers of His530Arg and Phe293Leu variants, may have a mixed etiology, as renal enlargement has been associated with another PRKAG2 variant, Arg531Gln." (PMID 40149727, 2025).
diabetes (3 papers, 2019 to 2025). "Nevertheless, variants in the UMOD and PRKAG2 loci, previously associated with eGFR and CKD in the general population, were associated with eGFR also in individuals with diabetes." (PMID 37324271, 2023). "Future mechanistic and translational work should determine whether persistent PRKAG2 stabilization represents a biomarker of adaptive neural metabolism or a viable target for interventions aimed at preventing diabetes-related neurodegeneration." (PMID 41282094, 2025). "Of these, genetic variants within the PRKAG2, encoding a protein kinase involved in cellular energy metabolism, have also been associated with eGFR in GWAS on kidney disease, both in individuals with and without diabetes." (PMID 37324271, 2023).
gout (3 papers, 2016 to 2022). A condition characterized by painful swelling of the joints, which is caused by deposition of urate crystals. "A similar opposing direction of association between European and Polynesian is also evident at other urate- and gout-associated loci PRKAG2 and HLF." (PMID 26808548, 2016). "Furthermore, PRKAG2 is one of the loci associated with hyperuricemia and gout." (PMID 34321071, 2021). "DNA hypomethylation at the PRKAG2 gene body (AMPK subunit gamma 2) was reported in gout patients compared to controls." (PMID 34321071, 2021). "Protein kinase AMP-activated non-catalytic subunit gamma 2 (PRKAG2) (cg09817217 and cg07012178), encoding the γ2 chain of AMPK, showed a gene body hypomethylation pattern in peripheral blood mononuclear cells of gouty arthritis patients." (PMID 35464445, 2022).
liver cirrhosis (3 papers, 2021 to 2023). "This was the first patient with PRKAG2 gene mutation reported to have liver cirrhosis; however, a functionality of the novel variant remains underdiagnosed." (PMID 33782433, 2021). "Notably, GSD-IX and GSD of the heart-lethal congenital (i.e. PRKAG2 deficiency) patients have been reported in Iran for the first time which shown the development of liver cirrhosis with novel variants." (PMID 33782433, 2021). "Furthermore, dysfunctional mutations in PRKAG2 have been proposed in liver cirrhosis." (PMID 36978128, 2023). "To the best of our knowledge, we report for the first time liver cirrhosis in GSD-X and GSD of the heart-lethal congenital (i.e. PRKAG2 deficiency)." (PMID 33782433, 2021).
Skeletal myopathy (3 papers, 2013 to 2020). "Interestingly, skeletal myopathy has been observed in patients with PRKAG2 mutations; ragged red fibres with excess mitochondria were detected but skeletal muscle biopsies of patients presented little glycogen accumulation." (PMID 24037260, 2013).
cognitive decline (2 papers, 2024 to 2025). "There has also been a previous association of PRKAG2 polymorphisms with cognitive decline in the elderly." (PMID 40757593, 2024). "In other contexts, single-nucleotide polymorphisms in the PRKAG2 gene have been identified to confer susceptibility or as potential risk factors for different clinical conditions, such as atopic dermatitis, diabetes in the elderly, and cognitive decline." (PMID 40757593, 2024).
Cognitive impairment (2 papers, 2015 to 2025). Abnormal cognition is characterized by deficits in thinking, reasoning, or remembering. "Accordingly, PRKAG2 expression has been shown to be elevated in AD and is associated with cognitive impairment in T2DM." (PMID 41282094, 2025). "Better performance in verbal memories and attention tasks has been found for specific genotype groups −26 polymorphism PRKAG2, indicating an active role of PRKAG2 in cognitive impairment." (PMID 25859259, 2015).
colon cancer (2 papers, 2014 to 2020). "Several genes in the backbone of the CHIEF pathway were associated with survival, including PIK3CA for colon cancer and PRKAG2, STK11, and TSC2 for rectal cancer." (PMID 25541970, 2014).
Glycogen storage disease of heart (2 papers, 2021 to 2024). "PRKAG2 (7q36.1) pathogenic variants have been previously linked to PRKAG2 cardiac syndrome or “AMPK disease”, including Wolff–Parkinson–White syndrome (WPWS), lethal congenital glycogen storage disease of the heart, and hypertrophic cardiomyopathy type 6." (PMID 40757593, 2024).
liver cancer (2 papers, 2021). An epithelial or non-epithelial malignant neoplasm that arises from the liver. "Conversely, the expression levels of ARNTL, NR1D1, PER1, PER2, PER3, PRKAG2, and RORA were not significantly related to the OS of liver cancer patients." (PMID 34149816, 2021).
Obesity (2 papers, 2021 to 2022). Accumulation of substantial excess body fat. "Furthermore, the chronic expression of PRKAG2 promotes hyperphagia and obesity." (PMID 33922358, 2021). "Agonists of PRKAG2, which is the subunit of AMPK (AMP-activated protein kinase), are proposed to treat obesity, BED, and BN." (PMID 33922358, 2021).
Sinus bradycardia (2 papers, 2017 to 2022). Bradycardia related to a mean resting sinus rate of less than 50 beats per minute. "Reminiscent of the sinus bradycardia of human R302Q PRKAG2 mutation carriers, invasive electrophysiology studies performed under isoflurane general anesthesia revealed a reduction in sinus HR of homozygous R299Q γ2 mice in vivo." (PMID 29097735, 2017). "We observed that humans carrying the R302Q mutation in PRKAG2 (the most frequently described) exhibit sinus bradycardia with a significantly lower resting HR compared with genotype-negative sibling controls." (PMID 29097735, 2017).
Alzheimer disease (1 paper, 2024). A progressive, neurodegenerative disease characterized by loss of function and death of nerve cells in several areas of the brain leading to loss of cognitive function such as memory and language. "The threefold increase in the PRKAG2 gene expression with raised AMPK levels is related to an increase in beta-amyloid accumulation in the brains of patients with Alzheimer’s disease." (PMID 40757593, 2024). "Thus, the higher the expression of the PRKAG2 gene, the more important the level of AMPK that occurs, and then, consequently, the abnormal metabolism and processing of the precursor protein occurs, leading to increased formation of beta-amyloid in individuals with Alzheimer’s disease." (PMID 40757593, 2024).
asthenozoospermia (1 paper, 2021). "The relative abundance in transcripts of few TH2B associated genes- CREM, CDYL, PRKAG2, CATSPERB, TSGA10 and TSSK1B was studied in sperm of fertile and infertile men with asthenozoospermia-, oligozoospermia- or oligoasthenozoospermia." (PMID 33933143, 2021). "PRKAG2 expression was significantly reduced in men with asthenozoospermia (p = 0.007), oligozoospermia (p = 0.009), and oligoasthenozoospermia (p = 0.02)." (PMID 33933143, 2021). "We observed Protein Kinase AMP-Activated Non-Catalytic Subunit Gamma 2 (PRKAG2) to be reduced in sperm of men with asthenozoospermia." (PMID 33933143, 2021).
Asymmetric septal hypertrophy (1 paper, 2022). Hypertrophic cardiomyopathy with an asymmetrical pattern of hypertrophy, with a predilection for the interventricular septum and myocyte disarray. "However, we also observed asymmetric septal hypertrophy in our PRKAG2 patients (LVWa = 1.42 ± 0.52)." (PMID 35509080, 2022).
Ataxia (1 paper, 2026). Ataxia refers to impaired coordination of voluntary muscle movement. "A diagnosis in patients aged <20 years was specific for all the syndromic causes of HCM (Danon, Friederich’s ataxia, NSML, mitochondriopathies, Pompe, Noonan, and PRKAG2)." (PMID 41574038, 2026).
breast carcinoma (1 paper, 2020).
channelopathy (1 paper, 2024). Channelopathies are a group of diseases caused by the dysfunction of ion channel subunits or their interacting proteins. "The variants included three channelopathy-associated genes (RYR2, CACNA1C, and ANK2), three HCM- or DCM-associated genes (MYH7, LDB3, and PRKAG2), five ACM-related genes (PKP2, JUP, DSG2, DSP, and TMEM43), and two cardiac transcription factor genes (TBX5 and GATA4)." (PMID 39272661, 2024).
Heart block (1 paper, 2024). Impaired conduction of cardiac impulse occurring anywhere along the conduction pathway. "The patient was found to have advanced heart block and PRKAG2 genetic mutation in the second hospitalization." (PMID 38937983, 2024).
Hyperglycemia (1 paper, 2019). An increased concentration of glucose in the blood. "Moreover, PRKAG2 (cg20406576) and EHMT2 (cg00210002) are hypomethylated in subjects with hyperglycemia, HOMA-IR ≥2.5 and hypertriglyceridemia." (PMID 30926763, 2019).
influenza infection (1 paper, 2013). "CREBBP, PRKCD are implicated in MAPK signaling which is crucial for viral protein production and export while PRKAG2 is implicated in post-entry processes and autophagy in influenza infection." (PMID 24116168, 2013).
Insulin resistance (1 paper, 2013). Increased resistance towards insulin, that is, diminished effectiveness of insulin in reducing blood glucose levels. "Furthermore, the PRKAG2 mouse model exhibits myocardial insulin resistance." (PMID 23829931, 2013).
Kleefstra syndrome 2 (1 paper, 2023). "A 7q36.1q36.2 deletion containing several pathogenic genes, including DPP6, KMT2C, ASB10, PRKAG2, KCNH2, among which KMT2C is a causative gene for Kleefstra syndrome 2 (MIM#617768)." (PMID 37892645, 2023).
liver failure (1 paper, 2021). A liver disease characterized by the liver losing or has lost all of its function. "Patient no.13 carried mutations associated with PRKAG2 gene, which also developed liver failure." (PMID 33782433, 2021).
lung carcinoma (1 paper, 2022). "For example, BMPR2, BRD7, PRKAG2, PRKAR1A and PPP2R2A (PP2A Bα subunit B55α), which are differentially expressed between group V (H+V−S+[M/T]) and groups II/IV (H+V+S−/H+V−S+[M]), play roles in tobacco-mediated lung diseases and lung cancers." (PMID 35642061, 2022).
lymphatic malformation (1 paper, 2024). Primary lymphedema is caused by anatomic or functional defects in the lymphatic system, resulting in chronic swelling of body parts and lymphatic-system malformation. "The association between PRKAG2, chylous effusion, and lymphatic malformations remains unclear." (PMID 39569283, 2024). "Further studies are required to assess the relationship between PRKAG2, chylous ascites, and lymphatic malformations." (PMID 39569283, 2024).
non-alcoholic fatty liver disease (1 paper, 2019). "Functional enrichment analysis indicated a relationship between insulin, insulin resistance, adipocytokine signaling pathway, and non-alcoholic fatty liver disease for PRKAG2 gene, a target gene of bta-miR-2419-5p." (PMID 31354792, 2019).
Noonan syndrome with multiple lentigines (1 paper, 2023). A rare multisystem genetic disorder characterized by lentigines, hypertrophic cardiomyopathy, short stature, pectus deformity, and dysmorphic facial features. "This is also the case for 8/14 syndromic HCM (CACNA1C, FLNC, PRKAG2, PTPN11 (Noonan), PTPN11 (Noonan syndrome with multiple lentigines), RAF1, RIT1, TTR), 3/12 DCM (DES, TNNC1 and TNNT2), and 2/6 ARVC (JUP, TMEM43) gene-disease pairs." (PMID 37872640, 2023).
Parkinsonism (1 paper, 2024). Characteristic neurologic anomaly resulting from degeneration of dopamine-generating cells in the substantia nigra, a region of the midbrain, characterized clinically by shaking, rigidity, slowness of movement and difficulty with walking and gait. "Our case report describes a sporadic late-onset presentation of WPWS associated with parkinsonism and ALS in the context of PRKAG2 variant, thus highlighting the potential importance of AMPK and PRKAG2 variant in the pathophysiology of late-onset MND/ALS and parkinsonism." (PMID 40757593, 2024).
radicular cyst (1 paper, 2021). "For radicular cyst, POLB and PRKAG2 genes were identified with A>G (rs2272615) of 0.83 and C>T (rs7429) of 0.79 polymorphism percentage in other African and other Asian population, respectively." (PMID 34539639, 2021).
renal dysfunction (1 paper, 2021). "When these five SNVs were evaluated in non-Hispanic Americans of European ancestry, only CACNA1D rs893365 and PRKAG2 rs7805747 continued to be associated with lower and higher odds of renal dysfunction 1-year post-transplant, respectively, after adjusting for covariates." (PMID 33868389, 2021). "The odds of renal dysfunction were higher in variant carriers of PPP3CC rs10108011, PPP3CC rs2461494, and PRKAG2 rs7805747, whereas the odds of renal dysfunction were lower in variant carriers of CACNA1D rs893365 and NR3C2 rs1490453." (PMID 33868389, 2021). "Additionally, the PRKAG2 rs7805747 variant A allele has been associated with higher odds of renal dysfunction in genome-wide association studies in non-transplant populations." (PMID 33868389, 2021).
renal fibrosis (1 paper, 2022). A final common manifestation of a wide variety of chronic kidney diseases characterized by glomerulosclerosis and tubulointerstitial fibrosis. "The status of NF-κB signaling modulated by PEBP4 could be similar to that regulated by microRNA-378, which activated NF-κB by targeting Prkag2, promoting renal fibrosis." (PMID 36120358, 2022).
schizophrenia (1 paper, 2024). A major psychotic disorder characterized by abnormalities in the perception or expression of reality. "ARL17B is implicated in schizophrenia, TPGS2 is found in the microtubule gene ontology term, and PRKAG2 is part of 4 pathways (AMPK signaling pathway, Lysine degradation, Cholinergic synapse, GnRH secretion) as well as the protein serine/threonine kinase activity gene ontology term." (PMID 38532526, 2024).
ventricular septal defect (1 paper, 2019). The presence of a defect (opening) in the septum that separates the two ventricles of the heart. "The phenotypic involvement of PRKAG2 expression may be realized in the previous ventricular septal defect self‐resolved and in the presence of short PR (up to 80 ms)." (PMID 31347270, 2019).
viral infection (1 paper, 2024). "The gene pair PRKAG2-BAD has the largest weight in the viral infection, indicating the neural network pays more attention to PRKAG2-BAD when reviewing samples with the viral infection." (PMID 38827397, 2024).
genetic disorder (6 papers, 2010 to 2026). "FVPs are associated with various genetic syndromes; however, a genetic disorder caused by PRKAG2 gene mutation is the special group which should be considered every time because of its specific and noteworthy clinical manifestations." (PMID 34974635, 2022).
cancer (5 papers, 2020 to 2026). A tumor composed of atypical neoplastic, often pleomorphic cells that invade other tissues. "Widespread shallow deletions for PFAS were also found in LUSC and PRAD, and copy number gains for PRKAG2 were found across the entire pan-cancer cohort." (PMID 36831501, 2023). "In addition, the gene expression profiles of Prkag2 and Pdcd1 were analyzed in resident Tregs in patient cancer specimens using the available datasets (GSE89225) (r = − 0.621, p = 0.0034)." (PMID 34649584, 2021). "This is followed by CFTR (18 cancer types) and four other genes that were amplified in 17 cancer types (ADIPOR2, LEP, PRKAG2 and RHEB)." (PMID 32807122, 2020).
kidney disease (5 papers, 2021 to 2024). "Biological annotation found evidence for three novel decline-associated loci to capture common-variant-effects for genes of rare Mendelian kidney diseases (SDCCAG8, RRAGD, and MUC1), additional to the two such genes in known eGFR-decline loci (UMOD, PRKAG2)." (PMID 39567532, 2024). "In this work, we discovered 20 top eccDNA hub genes in which NCAM1, NFATC1, PRKCB, LEF1, PRKAG2, and GRM8 were strongly linked to a variety of kidney disorders." (PMID 36967395, 2023).
metabolic disease (3 papers, 2017 to 2026). A congenital disorder (due to inherited enzyme abnormality) or acquired (due to failure of a metabolically important organ) disorder resulting from an abnormal metabolic process. "Most of these P/LP variants were found in validated minor sarcomere genes (ACTC1, MYL2 and MYL3) and genes related to metabolic diseases (GLA and PRKAG2)." (PMID 28771489, 2017).
infection (2 papers, 2023). The state of being infected such as from the introduction of a foreign agent such as serum, vaccine, antigenic substance or organism. "Conversely, cardiomyocytes expressing a constitutively active PRKAG2 variant that increases glucose transporters or LPS-treatment, increased infection, and amastigote proliferation." (PMID 36814444, 2023). "PRKAG2-mutant iPSC-CMs exposed to T. cruzi showed significantly increased infection and replication rates." (PMID 36814444, 2023).
myopathy (2 papers, 2013 to 2023). A disease of the muscle in which the muscle fibers do not function properly. "Overall, we found 103 clinically affected patients with cardiac involvement (and skeletal muscle glycogenosis and myopathy in some cases), who were investigated often along with family members who were carriers of PRKAG2 mutations." (PMID 37239976, 2023). "A PRKAG2 mutation was shown to cause myopathy in red muscle and ragged red fibres were observed with mitochondria accumulation but without substantial glycogen deposition." (PMID 24037260, 2013).
tumor (2 papers, 2013 to 2015). "We observed deletion of genes such as PRKAG2 in tumor tissue and PDXs, a key gene which inactivates enzymes of the fatty acid and cholesterol biosynthesis pathways (a precursor of sex steroids) and which may affect intra tumor sex steroid levels." (PMID 26695660, 2015).
autosomal dominant disease (1 paper, 2020). Autosomal dominant form of disease. "PRKAG2 cardiac syndrome is an autosomal dominant disease induced by a mutation in the PRKAG2 gene encoding the AMP-activated protein kinase γ2 regulatory subunit." (PMID 32296011, 2020).